ERGIC2 (ERGIC and golgi 2)
Description:
Possible role in transport between endoplasmic reticulum and Golgi.
Synonyms: ERV41; PTX1; CDA14; cd002
Tractability: Antibody: UniProt predicts a signal peptide or a membrane-spanning region. PROTAC: ubiquitination databases record sites on it; its protein half-life has been measured.
Gene: Protein-coding gene on chromosome 12 (29,337,352 to 29,381,189, reverse strand). Ensembl gene ENSG00000087502.
Subcellular location: Endoplasmic reticulum-Golgi intermediate compartment membrane; Golgi apparatus, cis-Golgi network membrane; Endoplasmic reticulum membrane; Cytoplasm; Nucleus
Subcellular location (Human Protein Atlas): Golgi apparatus; Vesicles; Nucleoli rim
Gene Ontology:
Molecular function: protein binding
Biological process: endoplasmic reticulum to Golgi vesicle-mediated transport; retrograde vesicle-mediated transport, Golgi to endoplasmic reticulum
Cellular component: cytoplasm; endoplasmic reticulum-Golgi intermediate compartment; Golgi apparatus; membrane; nucleolus; nucleus; retrograde transporter complex, Golgi to ER; transporter complex; COPII-coated ER to Golgi transport vesicle; endoplasmic reticulum; endoplasmic reticulum membrane; endoplasmic reticulum-Golgi intermediate compartment membrane
Genetic constraint (gnomAD): Loss-of-function variants: 7 observed, 10.37 expected, observed/expected ratio (o/e) 0.67, 90% interval 0.38 to 1.27. The upper end of that interval is the gene's LOEUF score, 1.27, which puts it in group 5 of 6, group 1 being the genes least tolerant of losing a copy. Missense variants: 140 observed, 159.87 expected, observed/expected ratio (o/e) 0.88, 90% interval 0.76 to 1.01. Synonymous variants: 46 observed, 47.98 expected, observed/expected ratio (o/e) 0.96, 90% interval 0.76 to 1.23.
Homologues: Orthologues: chimpanzee ERGIC2 (99% identical), macaque ERGIC2 (99% identical), guinea pig ERGIC2 (96% identical), mouse Ergic2 (95% identical), rat Ergic2 (95% identical), pig ERGIC2 (94% identical), zebrafish ergic2 (77% identical), tropical clawed frog ergic2 (76% identical), dog ERGIC2 (75% identical), zebrafish ERGIC2 (59% identical), Drosophila melanogaster CG4293 (34% identical), Caenorhabditis elegans ergi-2 (25% identical). Paralogues in human: ERGIC3 (32% identical), ERGIC1 (20% identical).
Diseases named in the same sentence as ERGIC2 in open-access papers:
ERGIC2 is named in the same sentence as 6 diseases in open-access papers, as found by Europe PMC text mining. Sharing a sentence is not in itself a finding about the gene and the disease. The quoted sentences say what the papers report.
head and neck squamous cell carcinoma (1 paper, 2022). A squamous cell carcinoma that arises from any of the following anatomic sites: lip and oral cavity, nasal cavity, paranasal sinuses, pharynx, larynx, and salivary glands. "However, a study in head and neck squamous cell carcinoma described a characteristic promoter methylation pattern of ZNF10, TMPRSS12, ERGIC2, and RNF215 genes, which was proposed as a biomarker of response to radiotherapy treatment." (PMID 35359376, 2022).
Intellectual disability (1 paper, 2023). "Furthermore, seven intellectual disability candidate genes, TM7SF3, STK38L, ARNTL2, ERGIC2, TMTC1, DENND5B and ETFBKMT have been identified." (PMID 37034680, 2023).
neurodevelopmental disorder (2 papers, 2023). A behavioral and cognitive disorder with onset during the developmental period that involves impaired or aberrant development of intellectual, motor, or social functions. "The results identified one potential KS candidate gene (TSPAN11), seven candidate genes for the neurodevelopmental disorder (TM7SF3, STK38L, ARNTL2, ERGIC2, TMTC1, DENND5B, and ETFBKMT), and four candidate genes for KS with ID (INTS13, REP15, PPFIBP1, and FAR2)." (PMID 37034680, 2023). "As a result, we identified a dozen candidate genes: TSPAN11 as a potential KS candidate gene, TM7SF3, STK38L, ARNTL2, ERGIC2, TMTC1, DENND5B, and ETFBKMT as candidate genes for the neurodevelopmental disorder, and INTS13, REP15, PPFIBP1, and FAR2 as candidate genes for KS with ID." (PMID 37563198, 2023).
ERGIC2 also shares sentences with these, for which no sentence is quoted: cancer (2 papers); tumor (2); psychosis (1).